ICAM1 (intercellular adhesion molecule 1)
Diseases named in the same sentence as ICAM1 in open-access papers (continued):
Sharing a sentence is not in itself a finding about the gene and the disease.
psychiatric disorder (9 papers, 2019 to 2024). A disorder characterized by behavioral and/or psychological abnormalities, often accompanied by physical symptoms. "Intercellular adhesion molecule 1 (ICAM-1) has been recognized in psychiatric disorders because of its putative role in neuroinflammation and the blood–brain barrier (BBB) function." (PMID 36904292, 2023). "When discussing the role of ICAM-1 in psychiatric disorders, it must be noted that increased expression and shedding of ICAM-1 is observed in a wide range of diseases, only a few of which are neuropsychiatric." (PMID 31824303, 2019). "The deviating ICAM-1 measures may indicate that dysregulation of the permeability of the BBB is a shared trait in numerous psychiatric disorders." (PMID 36895367, 2023). "Furthermore, ICAM-1 has been shown to play a key role in psychiatric disorders, and it is a marker for inflammation." (PMID 35860274, 2022). "Some studies investigated sICAM-1 levels in the cerebrospinal fluid of psychiatric disorders and ICAM-1 expression in postmortem CNS tissue of psychiatric patients and found that the overall duration and duration of the chronic phase of the psychiatric disorder seem to play a role in both." (PMID 31824303, 2019). "In addition, RT-qPCR analysis showed that the cytokine Tnf-α and the intercellular adhesion molecule-1 (Icam-1) were also elevated in the brain at this time, both of which are highly relevant to brain inflammation in context of psychiatric disorders (Capuron and Miller, 2011, Müller, 2019)." (PMID 34052363, 2021). "A specific, important aspect of ICAM-1 in psychiatric disorders might be its role at the BBB." (PMID 31824303, 2019). "For the following reasons, ICAM-1 is of particular interest: ICAM-1 has an important role in the functioning of the blood-brain barrier, and as such, ICAM-1 plays a significant role in the biology of the emergence and maintenance of psychiatric disorders." (PMID 36295659, 2022). "Although ICAM-1 levels may be affected by medication, in particular antipsychotics, ICAM-1 is mainly perceived as a marker of a blood brain barrier disruption and an inflammatory process in psychiatric disorders." (PMID 36895367, 2023).
immune diseases (7 papers, 2014 to 2026). "Collectively, IFNG, IL2RG, FCGR3A, and ICAM1 associated with immune diseases were selected from the core genes through manual screening." (PMID 40844079, 2025). "Through bioinformatics analysis, the core genes INFG, IL2RG, FCGR3A, and ICAM1 associated with immune diseases were screened and their expressions were also measured at the protein level." (PMID 40844079, 2025). "Our interaction network analysis revealed that ICAM1 is associated with GPS-infected immune diseases." (PMID 39202454, 2024). "MMP‐9, iNOS, ICAM‐1, and MCP‐1 were demonstrated to participate in the progression of inflammatory and immune disease." (PMID 37904675, 2023). "Subsequent Western Blot experimental results also confirmed the high expression of ICAM1 and SELL in UC, further emphasizing the importance of CCR7 in the pathogenesis of UC.The research on CCR7 in the field of immune diseases still holds boundless possibilities." (PMID 41481752, 2026).
neurodegenerative disease (7 papers, 2020 to 2024). A disorder of the central nervous system characterized by gradual and progressive loss of neural tissue and neurologic function. "It is well known that cell adhesion molecules, including ICAM-1, regulate both physiological interactions between neural cells and the extracellular environment and pathological mechanisms underlying neurodegenerative diseases." (PMID 32498476, 2020). "Similarly, microvascular injury biomarkers such as vascular cell adhesion molecule-1 (VCAM-1) and intracellular adhesion molecule-1 (ICAM-1) are released during global and regional cerebral hypoperfusion, a phenomenon associated with neurodegenerative diseases like AD." (PMID 32943089, 2020). "Although neurodegenerative diseases in general, and Parkinson’s disease (PD) in particular, are triggered and/or exacerbated by neuroinflammatory mediators, an association between ICAM-1 and PD has not been adequately studied." (PMID 39329738, 2024). "Given that neuroinflammation, underscored by microglial activation, is a key element in neurodegenerative diseases such as Parkinson’s disease (PD), we investigated whether ICAM-1 has a role in this progressive neurological condition and, if so, to elucidate the underpinning mechanisms." (PMID 39329738, 2024).
brain diseases (6 papers, 2015 to 2024). "rs12185519 was mapped to KDM4B, which has the potential to inhibit brain diseases such as AD by blocking ICAM1 and VCAM1‐induced extravasation." (PMID 39300745, 2024). "Our data suggest the potential of KDM4B inhibition for brain disease such as AD by blocking ICAM1 and VCAM1-induced extravasation." (PMID 28327608, 2017). "In the present study, we investigated the epigenetic regulatory mechanism of how inflammation regulates ICAM1 expression in endothelial cells and the role of ICAM1 in the pathogenesis of brain diseases such as AD." (PMID 28327608, 2017). "Thus, blocking ICAM1 or KDM4B could offer a novel therapeutic opportunity treating brain diseases." (PMID 28327608, 2017).
hematological cancer (4 papers, 2016 to 2022). "As opposed to LFA-1, ICAM-1 is present in several non-hematopoietic tumors where it can play different roles that also seem to be context dependent." (PMID 29099772, 2017).
respiratory diseases (4 papers, 2013 to 2025). "Inflammatory molecules, such as matrix metalloproteinases, COX-2, cPLA2, intracellular adhesion molecule-1 (ICAM-1), and vascular cell adhesion molecule-1 (VCAM-1), are implicated in the pathophysiology of respiratory disorders, including asthma and COPD." (PMID 40136649, 2025). "One of the earliest pathological changes in inflammation and respiratory diseases is the expression of cell adhesion molecules such as intercellular adhesion molecule-1 (ICAM-1) on epithelial cells." (PMID 29329563, 2018). "Various cytokines, such as IL2, IL4, IL6, IL8, and TNFα, and other inflammatory markers, such as intercellular adhesion molecule (ICAM) 1, soluble P-selectin, and CRP, have previously been associated with metal exposure or respiratory diseases." (PMID 25272992, 2014). "Increasing evidence has revealed the involvement of inflammatory proteins, including cPLA2, COX-2, VCAM-1, ICAM-1, and MMP-9, in the production and development of respiratory diseases." (PMID 40136649, 2025).
connective tissue disease (2 papers, 2017 to 2020). "Importantly, increased expression of Lgals3 and Icam1 was shown to be present in patients with IPAH and connective tissue disease." (PMID 31979420, 2020).
CNS tumors (1 paper, 2015). "Moreover, ICAM1 has been shown to play a pivotal role in physical and functional interaction between CNS tumors and CTLs." (PMID 26528477, 2015).
inflammatory myopathies (1 paper, 2013). "In contrast, myofiber expression of ICAM-1 has been observed in muscle biopsies obtained from patients with inflammatory myopathies." (PMID 23505517, 2013). "Induced expression of ICAM-1 by skeletal muscle cells has been reported after treatment of cultured human skeletal muscle cells with cytokines and in patients with inflammatory myopathies." (PMID 23505517, 2013).
ICAM1 also shares sentences with these, for which no sentence is quoted: multiple myeloma (20 papers); acute myocardial infarction (11); heart disease (6); chronic periodontitis (5); essential hypertension (5); Hyperinsulinemia (5); complication (4); diabetic cardiomyopathy (4); idiopathic pulmonary fibrosis (4); liver (4); acne (3); airway hyperresponsiveness (3); cystic fibrosis (3); delirium (3); genetic disorder (3); Impaired glucose tolerance (3); Multiple Organ Failure (3); polycystic ovary syndrome (3); skin sensitization (3); Splenomegaly (3); venous thromboembolism (3); abortion (2); acromegaly (2); biliary atresia (2); calcific (2); capillary leak syndrome (2); cerebral microbleeds (2); cerebral small vessel disease (2); chronic hepatitis B (2); chronic lung disease (2).
A further 206 diseases each share a sentence with ICAM1 in 2 papers or fewer.